BRCA1 (BRCA1 DNA repair associated)
Diseases named in the same sentence as BRCA1 in open-access papers (continued):
Sharing a sentence is not in itself a finding about the gene and the disease.
cancer (continued). "This combination synergically acts to block the growth of cancer cells: PI3K inhibition leads to downregulation of BRCA1/2 proteins which increase the degree of Homologous Recombination Repair (HRR) deficiency." (PMID 35565291, 2022). "Additionally, the 50% risk to pass the BRCA1/2-PV to a child may impact cancer worry." (PMID 34997316, 2022). "Although many high and moderate cancer genes have been discovered and associated with hereditary breast and ovarian cancer (HBOC) in the last years, BRCA1 and BRCA2 still account for most cases." (PMID 35898894, 2022). "The silenced BRCA1 and/or BRCA2 have been associated with the deficiency in the DNA double-strand repair and genomic instability, leading to cancer predisposition." (PMID 36160115, 2022). "DDR inhibitor (DDRi) therapy is used to treat cancer patients with tumors that harbor alterations in DDR proteins such as BRCA1/2." (PMID 36276148, 2022). "This vulnerability (synthetic lethality) initially allowed pharmacological inhibition of PARP to be exploited in BRCA1/2 deficient cancer, which is now being extended to BRCA proficient cancer." (PMID 35163965, 2022). "Although they appear to be open to receiving information on genetic mutations and their consequences for health, they are less likely to actively seek, test and screen for BRCA1/2-related cancer risks, underestimating the likelihood of developing cancer." (PMID 35303741, 2022). "PARP inhibitors also induce apoptosis processes and are standard molecular therapeutic drugs for BRCA1/2-defecient cancers." (PMID 35372044, 2022). "Core (BRCA1/2, PALB2), and any HRR mutations (BRCA1/2, PALB2, CHEK2, FANCA, ATM) occurred in 13 (10.3%) and 22 (17.5%) cancers, respectively." (PMID 36124727, 2022). "Cancer patients with defective BRCA1 had significantly shorter overall survival outcomes than those with normal BRCA1." (PMID 35517499, 2022). "Functional deficits in genes responsible for DNA damage repair (DDR) involved directly or indirectly in homologous repair recombination (HRR), such as BRCA1 and BRCA2, are associated with an increased risk for multiple types of cancer." (PMID 35907135, 2022). "This is consistent with our findings of significantly earlier cancer development in carriers with mutations in both PPARGC1A and BRCA1/2, as well as lower PPARGC1A expression in the PPARGC1A mutation carriers." (PMID 35625955, 2022). "Of all 577 BRCA1/2-PV carriers, 320 (57%) had high (≥ 14) cancer worry pre-surgery, and 54% had lower worry 12 months post-surgery than pre-surgery." (PMID 34997316, 2022). "In a recent study assessing the occurrence of HR-related mutations across several cancers, HRD was reported in 5% of NSCLC patients and 2% of BRCA1/2 variants were pathogenic in this population." (PMID 35511434, 2022). "Our work aimed to clarify the role of BRCA1 in the sensitivity to anti-cancer drugs (doxorubicin, paclitaxel, and cisplatin)." (PMID 36193432, 2022). "Hypermethylation of tumor suppressor genes including MutL homolog 1 (MLH1), breast cancer 1 (BRCA1), FA complementation group F (FANCF), and checkpoint with forkhead and ring finger domains (CHER) is implicated in cancer development." (PMID 36307808, 2022). "While BRCA1 was discovered by virtue of its roles in cancer biology and its genomic activities, accumulating evidence indicates that BRCA1 displays a spectrum of actions that do not fall within the classical cancer-related types of action." (PMID 35432218, 2022). "Women with more time since BRCA1/2-PV diagnosis were less likely to have high stable (OR 0.9) or high declining cancer worry (OR 1.0)." (PMID 34997316, 2022).
cancer (continued). "If the cells were treated with dobutamine beforehand, weaker BAX signals were observed in the IR-irradiated control and BRCA1 knock-down A2780 cells, and 13.7 and 14.5% cancer cells were BAX positive, respectively." (PMID 35517499, 2022). "Although PARP inhibitors are approved as therapeutics for specific cancers with defective BRCA1/2 genes, blocking PARylation can also activate adipogenesis and/or cell survival." (PMID 36077221, 2022). "Therefore, the procedure of ovarian tissue freezing should be limited to patients carrying mutations in BRCA1/2 genes in whom hormonal stimulation cannot be performed or who require immediate oncological treatment, mainly due to the risk of autotransplantation of ovarian tissue with cancer cells." (PMID 35887761, 2022). "In recent years, platinum (Pt) drugs have been found to be especially efficient to treat patients with cancers that lack a proper DNA damage response, for example, due to dysfunctional BRCA1." (PMID 36467895, 2022). "This study aimed to compare the intent to undergo BRCA1/2 testing, risk-reducing salpingo-oophorectomy (RRSO), and risk-reducing mastectomy (RRM) among the general public, cancer patients, and healthcare professionals in Korea." (PMID 35629239, 2022). "With the knowledge that SSBs that were unresolved by PARP1 became DSBs with replicative stress that requires BRCA1/2 for repair, the idea of cancer DNA damage response (DDR) synthetic lethality was tested." (PMID 35800362, 2022). "Even though the use of Olaparib is currently recommended for cancer patients with germline BRCA mutations, PARPi have been demonstrated to be efficient as sensitizing agents in cell lines with BRCA1/2 wild-type tumors." (PMID 35326611, 2022). "HMMR overexpression in mouse mammary epithelium increases Brca1-mutant tumorigenesis by modulating the cancer cell phenotype and tumor microenvironment." (PMID 35393420, 2022). "Thus, further elucidation of the regulation of fork protection in both BRCA1-proficient cells and BRCA1-deficient cells is important for the understanding of the mechanisms of genome maintenance and the development of novel approaches to overcome cancer resistance to PARPi." (PMID 35779634, 2022). "High levels of cancer worry (≥ 14) were identified in 320 women pre-surgery: 57% of the BRCA1-PV and 58% of the BRCA2-PV carriers." (PMID 34997316, 2022). "With the adoption of a larger 30 genes panel in our previous study, 15 probands that carried uncertain significance (Class 3) BRCA1 and BRCA2 variants were found to carry mutations in other cancer predisposition genes with high to moderate penetrance." (PMID 35641994, 2022). "Even talazoparib has been used to treat cancer patients with mutations in BRCA1/2, but recent findings have reported that in some TNBC cell lines, PARP inhibitors are effective in non BRCA1/2 mutation carriers." (PMID 36145297, 2022). "The role of mTOR in sustaining HSP90 and BRCA-1 expression level in stressed cancer cells was demonstrated in this setting by using NVB-BEZ-235, dual mTOR inhibitor that strongly downregulated both proteins." (PMID 35752616, 2022). "Promoter hypermethylation and mutational silencing of HR and MMR genes, such as RB, BRCA1/2, PTEN, MLH1, MSH3, MSH6 have been identified in human cancer." (PMID 36076047, 2022). "As expected, a stronger BAX signal was detected in the BRCA1 knock-down cancer cells upon IR irradiation, and the percentage of BAX-positive cells increased to 61.2%." (PMID 35517499, 2022). "Loss of function mutation of breast cancer genes 1/2 (BRCA1 and BRCA2) significantly increases the risk of development and progression of breast and other cancers." (PMID 35163965, 2022).
cancer (continued). "There is also regulation of BRCA1 gene expression by the Rb-E2F pathway in murine and human cancers." (PMID 35740092, 2022). "Accordingly, ATF6 silencing induced a stronger DNA damage in terms of γH2AX expression level and further downregulated BRCA-1 in cancer cells stressed by DPE or Thapsigargin." (PMID 35752616, 2022). "BARD1 encodes a protein that regulates tumor suppression and cell growth, and interacts with the N-terminal region of BRCA1 (breast cancer gene 1)." (PMID 36430822, 2022). "The defected BRCA1/2 is the specific marker for the use of a synthetic lethal-based PARPi (poly ADP ribose polymerase inhibitors) therapy in cancer treatment." (PMID 36497135, 2022). "As olaparib is not toxic to cells proficient in HR, such as the cells of the TME, and given the high abundance of macrophages in the TME of BRCA1/2-mutant cancers, we examined how PARP inhibition modulates tumor macrophage function." (PMID 36223740, 2022). "PV were detected in 13 cancer predisposition genes including ATM (n=4), BLM (n=1), BRCA1 (n=1), BRCA2 (n=7), BRIP1 (n=1), CDKN2A (n=1), CHEK2 (n=9), FANCC (n=1), MUTYH (n=10), NBN (n=1), PALB2 (n=1), RAD51D (n=1) and STK11 (n=1)." (PMID 36091166, 2022). "This case-control study examines the association of BRCA1 and BRCA2 pathogenic variants with additional cancer types and their clinical characteristics in 100 914 Japanese individuals across 14 cancer types." (PMID 35420638, 2022). "Of note, two tumor suppressor genes with critical roles in double-strand break (DSB) repair, BRCA1 and BRCA2, are frequently mutated or deleted in several cancer types." (PMID 36284291, 2022). "Cancer cells harboring a defective BRCA1/2 gene, are unable to use the HRR pathway to repair DNA damage, and therefore require PARP proteins to aid single stranded DNA repair." (PMID 36230674, 2022). "If other known deficiencies, such as the loss of BRCA1/2, were also identified, an increased expression of CSB would predict an enhanced dependence of these cancer cells to BIR." (PMID 36142121, 2022). "Wwox absence leads to very early DSB-induced DNA end-resection and enhances pRPA, Rad51, Abraxas, Brca1, and CtIP foci formation beginning at 0.5 h post IR in mouse cells and even earlier end-resection in human cancer cells." (PMID 35409089, 2022). "For clinical practice, our results should be included in counselling BRCA1/2-PV carriers about expectations of cancer concerns over time." (PMID 34997316, 2022). "In this study, the frequency of co-occurring variants in both the BRCA1 and BRCA2 genes in the pan-cancer cohort was approximately 3%, which was somehow higher than that of most previous studies." (PMID 36147908, 2022). "Mutations in the genes involved in the breast cancer susceptibility gene (BRCA) signaling pathway, namely BRCA1, BRCA2, and PALB2, have been found in a subset of PDAC." (PMID 36556296, 2022). "If the attenuations in the PRS effect size are real, they would result in a smaller range of cancer risks for BRCA1 and BRCA2 carriers compared with using the PRS effect sizes estimated from general population data." (PMID 34320204, 2022). "Our further analysis revealed that in Brca1-WT cancer cells, ATP11b and Ptdss2 signaling also plays similar roles in cancer metastasis." (PMID 35025764, 2022). "Pan-cancer, we detected 111 (1.3%) BRCA1 hypermethylated cases, whereof 50 were strongly hypermethylated and 61 were moderately hypermethylated." (PMID 35681079, 2022). "In this regard, numerous molecular oncology studies have been conducted over the last decade to investigate the impact of BRCA1/2 genetic alterations and their role in cancer." (PMID 35986351, 2022).
cancer (continued). "Distribution of BRCA1 and BRCA2 pathogenic variants tested in the National Cancer Control Programme of the Ministry of Health for the years 2018–21 (n = 3,458)." (PMID 36171877, 2022). "ATR inhibition has been shown to disrupt BRCA1-independent loading of RAD51 at DSBs causing stalled forks and to be effective in overcoming resistance to PARP inhibitor in cancer cells exhibiting BRCAness." (PMID 36123603, 2022). "Each subsequent cycle of chemotherapy not only demethylates more cells at the BRCA1 promoter, but also progressively enriches for these partially methylated cells as the more chemosensitive fully BRCA1 methylated cancer cells are progressively eliminated." (PMID 35857626, 2022). "BRCA1 overexpression significantly increased the IC50 index for doxorubicin, paclitaxel, and cisplatin compared with MCF-7-LXSN cells, indicating that BRCA1 promotes the sensitivity of MCF-7 cells to anti-cancer treatment." (PMID 36193432, 2022). "The analysis of BRCA1/2-driven cancers revealed that these tumors are characterized by accumulation of LOH, which are larger than 15 Mb in size but do not involve the entire chromosomes." (PMID 36361916, 2022). "Pre-clinical investigations determined that dysfunction of BRCA1/2 results in sensitization of cancer cells to the catalytic inhibition of Poly ADP-ribose polymerase (PARP), producing cell-cycle arrest followed by apoptosis." (PMID 35163965, 2022). "In AYA BRCA we identified more frequent FANCM, FANCD2, and BRCA1 mutations when controlling for TMB, suggesting the role of DNA damage repair in this cancer type." (PMID 36433963, 2022). "Female carriers of germline pathogenic/likely pathogenic variants (P/LPVs) in the BRCA1/BRCA2 (BRCA) genes are at a substantially increased lifetime risk for developing breast, ovarian, and (to a lesser extent) other cancer types." (PMID 36230512, 2022). "To elucidate the mechanism by which TRIM44 orchestrates BRCA1-mediated HR repair and cisplatin resistance, we reviewed all publications linked to TRIM44 in cancer." (PMID 35541909, 2022). "Carriers of deleterious heterozygous germline mutations in the BRCA1 and BRCA2 genes have high risk of different types of cancer, such as PCa." (PMID 35740437, 2022). "Across distinct cancer subtypes, the Catalogue Of Somatic Mutations In Cancer (COSMIC) Signature 3 (cSig3) was closely associated with BRCA1/2 mutations." (PMID 36230674, 2022). "They revealed that RSV was able to activate Sirt1 and inhibit the expression of survivin leading to a greater inhibitory on Brca1 mutant cancer cells than on Brca1-wild-type cancer cells." (PMID 35327559, 2022). "In BRCA1/2 defective cancer cells, when the backup DNA repair pathways are disrupted, PARPi can induce synthetic lethality." (PMID 36159999, 2022). "This CtIP function is even more important in cells with diminished fork protection due to BRCA1 defects, suggesting CtIP as a novel therapeutic target to augment genotoxic cancer therapy of tumors with BRCA1 defects." (PMID 36203968, 2022). "At least four PARPi (Olaparib, Rucaparib, Talazoparib, Niraparib), which are synthetic lethal with BRCA1-deficiency, have been approved by FDA for treating various cancers." (PMID 35779634, 2022). "Five of these cancer types (OV, LUSC, STAD, BLCA, and BRCA) overlapped with top ten cancer types in the list ordered by the frequency of BRCA1/2 alterations." (PMID 35681079, 2022). "Although commonly grouped together in most datasets, BRCA1 and BRCA2 have several differentiating roles in cell function as well as different implications for cancer risk and treatment response across tumour types." (PMID 36497408, 2022).
cancer (continued). "BRCA1/2 carriers were also more likely to have positive family history of any cancer (OR: 3.969, 95%CI (1.623–9.71), p = 0.002)." (PMID 34206661, 2021). "This study supports the idea that the role of BRCA1 in R-loop homeostasis is involved in the suppression of tumour formation, but more studies are needed in order to ascertain the potential role of COBRA1 in cancer development upon BRCA1 malfunction." (PMID 33755171, 2021). "Tissue specificity in cancer is best evidenced by hereditary cancer predisposition syndromes in which the underlying gene defects, such as mutations in APC, BRCA1, and VHL, are associated with a high risk of developing tissue-specific cancer types." (PMID 34440884, 2021). "Defects in HR, as exemplified by loss of BRCA1 or BRCA2 function, are associated with increased risk of breast, ovarian, prostate, pancreatic, and other cancers." (PMID 34481156, 2021). "The overall incidence of cancer for our study cohort was 1·9%, which is similar to the 2·4% reported in the BRCA1 and BRCA2 cohort of IMPACT and lower than the 4·3% of men diagnosed in the first screening round of the ERPSC." (PMID 34678156, 2021). "We confirmed a higher earliness frequency of cancer onset with BRCA1 than BRCA2 for the youngest age groups as well." (PMID 34356116, 2021). "It is therefore postulated that the BRCA1 mutations that allow ACC1 de-phosphorylation underlie the high FA synthesis that characterizes pathological states, such as in cancer." (PMID 34884734, 2021). "It is worth noting that our results of olaparib resistance in different BRCA1 mutant cells due to EMI1 downregulation that were associated with high RAD51 levels are in line with previous results done either in BRCA1 mutant cancer cells or BRCA2 mutant ones." (PMID 33412559, 2021). "DNA extracted from the cancer tissue of these patients was used to prepare a library and to sequence all coding regions of the BRCA1/2 genes." (PMID 33918338, 2021). "A2780 and SKOV3 cells are wild-type BRCA cancer cells, while UWB1.289 and SNU-251 cells have deleterious BRCA1 mutations." (PMID 34919531, 2021). "A stapled peptide targets CtIP tetramers to inhibit DNA repair and exert synthetic lethality in BRCA1-mutant cancer cells." (PMID 33608267, 2021). "This includes promoters for TSGs, such as MLH1 and BRCA1, which in some cancer types were significantly hypermethylated after using MethylDriver but not by testing without correction." (PMID 34871444, 2021). "Given CCNE1 amplification and BRCA1/2 mutations are mutually exclusive, there is thought that CCNE1 amplified cancers are reliant on a proficient homologous recombination pathway." (PMID 34485660, 2021). "We conducted a similar multivariate regression analysis for somatic mutations, and identified 24 significant associations in five (i.e., BRCA1, BRCA2, ATM, ATR, CHEK2) genes and higher HRD (FDR < 0.05) across cancer types." (PMID 34572800, 2021). "Several cancer-associated genes have been identified on chromosome 17q, including PPM1D, EME1, BRCA1, ERBB2, NF1, RAD51C, BRIP1 and BIRC5." (PMID 34885154, 2021). "MBC patients who were carries of P/LPVs in BRCA1 or BRCA2 were more likely to report a family history of other HBOC-related cancers in first- and/or second-degree relatives (70% vs. 29.5%, p = 0.001)." (PMID 33891299, 2021). "Next-generation sequencing studies successfully identified frequent mutations in multiple cancer types and genes involved in HRR that go beyond BRCA1/2." (PMID 34712892, 2021). "Some authors have tried to set up different methods for VUS classification for the BRCA1, BRCA2, and the PALB2 genes in order to predict variant pathogenicity and the resulting susceptibility to cancer." (PMID 34206535, 2021).